LINC01322 (long independently transcribed non-coding RNA 1322)
Synonyms: RUS
Gene: Long non-coding RNA gene on chromosome 3 (165,206,440 to 165,846,519, forward strand). Ensembl gene ENSG00000244128.
Diseases named in the same sentence as LINC01322 in open-access papers:
LINC01322 is named in the same sentence as 4 diseases in open-access papers, as found by Europe PMC text mining. Sharing a sentence is not in itself a finding about the gene and the disease. The quoted sentences say what the papers report.
glioblastoma multiforme (1 paper, 2024). "Interestingly, LINC01322 was also up regulated in The Cancer Genome Atlas Program (TCGA) cohorts for pRCC, ccRCC, head and neck squamous cell carcinoma (HNSC), and glioblastoma multiforme (GBM)." (PMID 39886373, 2024).
cancer (2 papers, 2021 to 2022). A tumor composed of atypical neoplastic, often pleomorphic cells that invade other tissues. "Some of the irlncRNAs previously associated with the malignant phenotypes of various cancers, including MIAT, TYMSOS, LINC01063, HOXC-AS1, LINC02454, SCAT1, and LINC01322 were identified in the process of modeling in this study." (PMID 34167440, 2021). "The roles of LINC01322 and CALML3 in cancers were also revealed by previous studies." (PMID 35433477, 2022).
tumor (1 paper, 2024). "RCC tumors with LINC01322 up regulation had bigger size compared with tumor with LINC01322 down regulation." (PMID 39886373, 2024). "Interestingly, the tumors with LINC01322 up regulation had bigger size compared with tumor with LINC01322 down regulation (6.14 ± 1.26 vs. 3.84 ± 0.46, cm)." (PMID 39886373, 2024).
LINC01322 also shares sentences with these, for which no sentence is quoted: head and neck squamous cell carcinoma (1 paper).